INS (insulin)
Diseases named in the same sentence as INS in open-access papers (continued):
Sharing a sentence is not in itself a finding about the gene and the disease.
cancer (continued). "Increased levels of insulin and IGF-1 can would promote tumors growth and progression by binding to the overexpressed insulin receptor in many cancers." (PMID 35463353, 2022). "The pathways enriched with MI-gene are found related to cardiovascular system development, blood circulation, response to wounding, positive regulation of locomotion, cancer, HIF-1 signaling pathway, insulin resistance and TGF-beta signaling pathway." (PMID 34900127, 2021). "Lastly, we think that it exist the crosstalk between cancer cells and macrophages in muscle tissues, it is that tumor cells secrete IL-6 inducing macrophages to up-regulate MMP12 which degrade insulin and IGF-1 in muscle tissue." (PMID 34863141, 2021). "This seems to be due both to the complexity and the homology that is shared by insulin and IGF receptors and to the knowledge gap regarding the cross-talk between cancer cells and the stroma in the pancreas." (PMID 34440625, 2021). "The pilot program started with two biotherapeutic products used for cancer treatment in the WHO Essential List in July 2018 and this was expanded to include insulin in November 2019." (PMID 33222245, 2021). "These were novel findings that show how insulin and IGF1 downstream signaling cascades differ in cancer cells; however, the mechanisms for these differences were obfuscated by the distance of E-cadherin and ACC from the InsR and IGF1R signaling pathways." (PMID 34191793, 2021). "It relays the molecular crosstalk to mediate the development of hallmarks of cancer, directly via its target genes such as IGF2, CD18, VEGF, FN1, GLUT1 and BCL2 and indirectly by inducing other factors such as insulin, leptin and negatively regulating PTEN." (PMID 34225729, 2021). "Being part of the so-called insulin–insulin-like growth factor (IGF) axis, insulin and IGF exert growth promoting and antiapoptotic activities in cancer cells that are mediated through a complex signaling network." (PMID 34202040, 2021). "The receptors for insulin and insulin-like growth factor (IGF-1) are ubiquitously expressed in cancer cells." (PMID 35052581, 2021). "Although not tested in the context of cancer, increasing adipose tissue insulin sensitivity by exercise could lower cancer-associated accelerated lipolysis to protect against cancer cachexia, as tissue loss can be prevented by lipolysis inhibition in preclinical rodent models." (PMID 33801684, 2021). "Downregulated proteins were overrepresented when cells were treated with 10 ng/mL of insulin were related with protein digestion and absorption (n = 3), extracellular matrix (ECM)–receptor interaction (n = 3), and proteoglycans in cancer (n = 4)." (PMID 33693651, 2021). "Long-lived Ghr–/– mice have elevated subcutaneous fat mass, APOE and insulin sensitivity of cardiac and skeletal muscle, but lower body weight, plasma cholesterol, IGF-I, plasma insulin, glucose tolerance, and cancer." (PMID 34074802, 2021). "Taken together, these results indicated that in our mouse model of cancer‐cachexia, skeletal‐muscle specific over‐expression of SIRT6 increased plasma insulin levels, which likely contributed to reduce tumour growth and to preserve muscle mass." (PMID 34212132, 2021). "Damage to the gastrointestinal tract and liver may also impair insulin sensitivity; gut motility is impaired not only by cancer treatment, but also via dysbiosis of the intestinal microbiome by effect of diet restriction and antibiotics, which are also commonly used during cancer treatment." (PMID 33802940, 2021). "For instance, insulin secretion, circadian rhythm, and calcium signalling were enriched in adult, while carbon metabolism, PI3-Akt, and proliferation related annotations (cancer) were enriched in P10." (PMID 33888791, 2021).
cancer (continued). "The combined treatment of CD24-targeted lentivirus particles together with INS or INR2 peptides led to pancreatic (left, black bars) and lung (right, black bars) cancer cell death, as demonstrated by WST-1 (left) and MTT (right) enzymatic assays." (PMID 33958722, 2021). "In fact, insulin signalling via both the PI3K/AKT and MAPK pathways can contribute to cancer cell proliferation." (PMID 33477579, 2021). "Strategies that target insulin and IGF signalling for cancer treatment include ligand- or receptor-specific agents, as well as interventions that globally alter glucose homoeostasis." (PMID 33911195, 2021). "KEGG analysis identified adhesion, hematopoiesis and cancer-related proteoglycans as affected pathways (e.g. metformin: CD9, CTSL, IL5, HGF; insulin: EGF, EZR, PLCG2, TFRC)." (PMID 33690729, 2021). "PF and especially FMDs, because of their periodic use, limited burden on human subjects, and effects on IGF-1, insulin, glucose, IGFBP-1 and ketone bodies levels, have the potential for applications in cancer prevention and treatment." (PMID 34572814, 2021). "The insulin-, the IGF-1-, and the leptin-induced signaling cascades converge on activation of PI3K/AKT-mTOR pathway, which stimulates cancer cell proliferation and survival, the latter being also stimulated by the estrogen-induced CDK4/6." (PMID 33271979, 2020). "In addition, experimental studies have reported that dietary fiber may protect cancer by improving insulin sensitivity and metabolic regulation, reducing inflammation, modulating the gut microbiota, removal of damaged cells, diluting carcinogens, and decreasing transit time." (PMID 32778880, 2020). "The effect of insulin on cell migration and invasion was evaluated in a mesenchymal type (MDA-MB-231) and epithelial type (MCF-7) cancer cells." (PMID 32631390, 2020). "Homeostasis regulation of insulin and IGF-1 levels activate various pathways to mediate cell proliferation and survival, which can promote cancer cell proliferation and invasion or inhibit apoptosis." (PMID 32370764, 2020). "Apart from insulin and IGF1 (insulin-like growth factor 1) signaling, there is compelling evidence for the CRC-promoting role of hyperglycemia per se as cancer cells require high amounts of glucose due to the Warburg effect." (PMID 32971867, 2020). "Bioinformatic analysis demonstrated that differentially expressed miRNAs were associated with pathways regulating metabolism, survival, and cancer development such as the PI3K-Akt, ErbB, mTOR, and MAPK, insulin signaling pathways." (PMID 33133155, 2020). "Accordingly, inhibition of insulin, IGF-1, and leptin by fasting can co-operate with blockade of estrogen and CDK4/6 to abrogate cancer cell proliferation and survival." (PMID 33271979, 2020). "Based on previous literature, we have presented a summarized figure where we have shown the common and two well-studied signaling pathways for the insulin and insulin receptor and IGF-1 and IGF-1 receptor as well as for both cancer and diabetes." (PMID 33552973, 2020). "HDAC1 inhibitors such as MS-275 have already been tested in many clinical trials for anti-cancer treatment 23, 46, thus they could be clinically effective tools to enhance β-cell function through triggering serotonin production, as supported by amplified insulin response in MS-275-injected mice." (PMID 32641996, 2020). "There are anti-cancer therapies under clinical trials which target the IGF/IGF-receptor system, however, most of them failed due to interfering with insulin signaling and manifesting metabolic toxicity." (PMID 32133294, 2020). "Similar to CR animals, dwarf mice are protected from spontaneous and chemically induced cancer, age-dependent declines in immune function, collagen cross-linking, decreased levels of insulin and IGF-1, and increased insulin sensitivity." (PMID 32708786, 2020).
cancer (continued). "By lowering elevated insulin levels it reduces activation of the PI3K-mTOR pathway, which is responsible for cell survival and proliferation in cancer." (PMID 31518336, 2019). "We identified important cancer related pathways, pancreas specific pathways, AGE-RAGE signaling, prolactin signaling and insulin resistance signaling pathways among the most affected ones." (PMID 31795960, 2019). "However, because weight loss after cancer diagnosis is associated with poorer outcomes, interventions that cause little to no weight loss but reduce insulin concentrations out of proportion to body weight change may be attractive targets." (PMID 31867105, 2019). "Genes related to metabolic, cancer, focal adhesion, MAPK- and insulin signaling are among the most significant over-represented pathways." (PMID 31921306, 2019). "Every stimulation of cancer cell lines missing IR lead to down-regulation of DOK genes, whereas in control cell line with IR insulin or IGF1 stimulation resulted in up-regulation of DOK genes expression." (PMID 30929166, 2019). "Using this approach, miR-4666-3p was predicted to target various cancer-related signaling pathways, including the TGF-β, mitogen-activated protein kinase (MAPK) and insulin signaling pathways, which comprised 33 target genes." (PMID 31824844, 2019). "In mammals, function crosstalk between insulin/IGF-I and G-protein coupled receptor (especially Gq-coupled GPCR) have been well-documented and believed to play a role in cancer progression, e.g., in pancreatic cancer." (PMID 31412674, 2019). "TNFα, produced by macrophages, may act as a metabolic hormone blocking insulin signaling or production, as TLRs do, but also as a regulator of the immune response, therefore being a representative molecule linking inflammation, metabolism, immune response, and cancer." (PMID 30764482, 2019). "Among gene sets used in GSEA, we found frequent up-regulation of cancer pathways across factors, including MAPK, ERBB-family, and insulin signaling pathways." (PMID 31695042, 2019). "Insulin and insulin-like growth factor-1 (IGF1) are regarded as important players in cancer biology." (PMID 31771180, 2019). "While preclinical data suggest that cancer treatment may be enhanced via inhibiting these proteins with antagonist molecules, downregulation by means of intense lifestyle changes, dietary alterations, or modulation of insulin/glucose through diabetic medication remains less clear in practice." (PMID 30101126, 2018). "Ectopic fat deposition is related to metabolic abnormalities and defects in insulin sensitivity, T2DM, cardiovascular disease, and cancer." (PMID 29697773, 2018). "Various pathways were activated in the MPC1± mice, including carbon metabolism, AMPK signaling pathway, insulin signaling pathway, oxidative phosphorylation, pyruvate metabolism, fatty acid metabolism, TCA cycle, and cancer pathway." (PMID 30397542, 2018). "A study of the role of insulin and IGF-1 in energy balance and cancer showed that the expression of genes related to the IGF pathway is modified by the absence of physical activity." (PMID 29484135, 2018). "In TC, IR is predominantly expressed as the “pro-mitogenic” isoform A (IR-A), which binds—with high affinity—to not only insulin, but also to IGF-2, which is produced by cancer cells in autocrine manner." (PMID 30513575, 2018). "In conclusion, the present study adopted the concepts of “glucose and insulin-induced CA125” and “dynamic measurement/assessment of serum cancer biomarkers”." (PMID 29716620, 2018). "The highest number of molecules in this data was part of the PKA cascade, followed by mechanisms of cancer, AMPK, GPCR, Insulin, MEK-ERK, and Synaptic Long Term Potentiation (SLTP)." (PMID 29391485, 2018). "The action of metformin on cancer cells depends on a direct effect mediated by AMP kinase and indirect action mediated by circulating insulin to decrease insulin receptor levels together with reduction in AKT and ERK 1/2 phosphorylation." (PMID 29500444, 2018).
cancer (continued). "The altered metabolism of hormones, especially insulin, insulin-like growth factors and sex steroids, as well as the disturbed secretion of adipokines, have been proposed as plausible mechanisms that may encourage or promote cancer occurrence or progression in obese individuals." (PMID 30429670, 2018). "Fenretinide is known to have a breadth of effects on cell homeostasis, interfering with retinol binding and transport, cell survival, inducing apoptosis in cancer and RPE cells, and improving insulin sensitivity and glucose homeostasis in vitro and in vivo." (PMID 28448568, 2017). "Circulating insulin and IGF-1 primarily converge with intrinsic cancer cell metabolic processes via binding to their cell surface receptors, specifically insulin receptor (IR) and IGF-1R." (PMID 28959684, 2017). "Moreover, nutrient-promoted insulin secretion and mTOR activation are temporary and reversible processes that are relieved by nutrient removal, indicating that overnutrition does not promote cancer onset through promoting mutations." (PMID 28878358, 2017). "The insulin/IGF-1 signaling pathway plays an important role in cell proliferation, apoptosis, and cancer." (PMID 29250031, 2017). "This review discusses how the insulin/IGF system integrates with glycosylation alterations and impacts on cell behaviour, metabolism and drug resistance in cancer." (PMID 28880250, 2017). "Overexpression of α-Klotho or treatment with sKl inhibits insulin/IGF-1-mediated downstream effectors IRS-1, Akt1, and ERK1/2 in cancer cells." (PMID 29250031, 2017). "Insulin is known to increase IGF-1 levels, which decreases cancer cell death and increases cancer cell growth." (PMID 26959117, 2016). "Previous studies showed that MAPK signal, which acts as downstream of insulin and IGF-1 proliferative signaling, plays a role in the proliferation of various cancers, including breast, colon and prostate cancer." (PMID 26901856, 2016). "Altered molecular responses to insulin and growth factors (GF) are responsible for late‐life shortening diseases such as type‐2 diabetes mellitus (T2DM) and cancers." (PMID 27613445, 2016). "Particularly activation of the insulin and IGF1 receptor triggers cancer-relevant intracellular signaling cascades." (PMID 27893783, 2016). "For instance, we determined that EGF and IGF-I, insulin and further tumorigenic factors like hypoxia and endothelin-1 up-regulate GPER expression in diverse cancer cell contexts." (PMID 27384677, 2016). "Previous studies have shown that insulin and IGF-1 have pro-proliferation effects in various cancer cells." (PMID 26901856, 2016). "In particular, this drug interferes with the insulin/IGF-1R system in tumor cells as shown in pancreatic, breast, endometrial, prostate and lung cancers." (PMID 27391065, 2016). "On the other, insulin signaling impairment also promotes liver gluconeogenesis, further increasing REE, tissue wasting and ultimately fueling cancer aerobic glycolysis." (PMID 26900952, 2016). "The insulin/insulin-like growth factor (IGF) system and related pathways such as growth hormone, and leptin signaling have a key role in cancer development." (PMID 27942580, 2016). "The modulation of plasma insulin and IGF-1 levels by pharmaceutical interventions is a promising approach for cancer treatment." (PMID 26878387, 2016). "Here we have found that, after adjusting for cumulative insulin exposure, people prescribed metformin in combination with insulin had a reduced risk of all-cause mortality in comparison with people prescribed insulin monotherapy, but no reduced risk of cancer was found." (PMID 27152598, 2016). "In mice, HCA1 mediates anti-lipolytic effects in an insulin dependent manner and regulation of the lipogenic/lipolytic balance is essential for HER2 overexpressing cancer cells to ensure rapid proliferation." (PMID 25839160, 2015).
cancer (continued). "For example, insulin or IGF-1 increased cell proliferation and reduced apoptosis in cancer cells, even at physiologically relevant concentrations." (PMID 25866823, 2015). "This speaks to the complexity of the insulin/IGF signaling system, whose activity can differ by cancer subtype and molecular environment." (PMID 26029167, 2015). "In the patient, there were losses of control pathway interactions with insulin and follicle stimulating hormone, and there were gains of interactions with MYC, a key transcription regulator in cancer." (PMID 26510912, 2015). "Treatment of cancer patients with an adequate SAART (e.g., Cys-, Gly-, Ser-, Leu+, Gln+?, insulin+)?" (PMID 26682277, 2015). "Insulin and IGF signaling play an important role in the development and progression of many cancers, as they can promote tumor cell proliferation, survival, migration, and invasion as well as angiogenesis." (PMID 26029167, 2015). "Many epidemiological studies have suggested that insulin and IGF-1 play important roles in the regulation of cancer." (PMID 25866823, 2015). "Numerous epidemiological and pre-clinical studies have demonstrated that the insulin/insulin-like growth factor (IGF) system plays a key role in the development and progression of several types of cancer." (PMID 26029167, 2015). "Metabolic stresses including Insulin/IGF-1 enhance the expression of TRB3 in a diversity of human tumour tissues and cancer cells." (PMID 26268733, 2015). "We speculated that the use of insulin therapies to control a hyperglycemic environment might also play a pivotal role in protecting some diabetic patients from carcinogenesis rather than the adverse effect of excessive exogenous insulin on IGF-I receptor resulting in cancer." (PMID 25978841, 2015). "It is now well established that the insulin/IGF system is frequently dysregulated in cancer, thus contributing to cancer progression, metastases, and resistance to cancer therapies." (PMID 25798130, 2015). "There is still a need for uncovering new ways to effectively target both insulin and IGF signaling in cancer while avoiding significant metabolic toxicity." (PMID 25699021, 2015). "TRB3 mediates insulin/IGF-induced reactive oxygen species production, DNA damage, increase in S-phase fraction, evasion of apoptosis and proliferation in cancer cells, whereas silencing TRB3 impedes the malignancy-promoting actions." (PMID 26268733, 2015). "The mitogenic effect of insulin and IGF is due, in part, to activation of the PI3K pathway, one of several targets of metformin which is currently being investigated as an anti-cancer drug." (PMID 26192445, 2015). "It is worth noting that the activation of the PI3K pathways is required for insulin-induced upregulation of vascular endothelial growth factor (VEGF), which sustains neoangiogenesis and, thus, cancer progression." (PMID 26171112, 2015). "Second, the insulin and IGF cancer-related signaling pathways have adapted from those of normal cells, particularly from insulin-sensitive tissues such as the liver, muscle, and adipose tissue." (PMID 25866823, 2015). "The insulin/insulin-like growth factor (IGF) system is a multifactorial signaling network that modulates energy metabolism, cell growth, and cancer." (PMID 26528439, 2015). "IR-A expression is increased in cancer cells, including HCC, and primarily promotes the mitogenic role of insulin, while IR-B primarily controls insulin’s metabolic effects." (PMID 26441826, 2015). "Elevated levels of insulin and INSR have been reported in several human cancers, including breast, colon, and lung, suggesting the existence of a common etiological link." (PMID 24434591, 2014). "Both insulin and IGF-1 induce proliferation and inhibit apoptosis in various cancer cell lines, including ovarian." (PMID 25026276, 2014). "Insulin and IGF1 are growth factors with putative regulatory roles in proliferation, survival and cancer progression." (PMID 25373319, 2014).